CD4 (CD4 molecule)
Diseases named in the same sentence as CD4 in open-access papers (continued):
Sharing a sentence is not in itself a finding about the gene and the disease.
lung cancer (continued). "Opposingly, activin treatment reduced the tumor burden, increased the survival time, and increased the pro-inflammatory profile of isolated CD4+ T-cells in a Lewis lung carcinoma (LLC) mouse model of lung cancer." (PMID 37296966, 2023). "For example, it has been reported that CD4+ T cells downregulate IFN-y after activation in lung cancer (we used the hamster lung cancer cell line HT100) through hypermethylation of the IFNG promoter (mechanism of tumour mediated immune suppression)." (PMID 36817448, 2023). "Mediastinal lymph nodes of patients with IPF exhibited increased CD4/CD8 ratio compared to patients with lung cancer." (PMID 37964265, 2023). "This is consistent with previously reported results that cantharidin combination therapy will promote increases in CD8 + T cells and CD4 + Teff cells among tumour infiltrating lymphocytes to inhibit lung cancer growth." (PMID 38017425, 2023). "Re-invigoration of exhausted T cells is likely to be relevant because murine lung cancer induces generalised T cell exhaustion in both CD4+ and CD8+ T cells." (PMID 37957274, 2023). "We found that classical Th1 and Th7R were equally present in lung cancer tissues as Th1-like CD4+ T cells, with few Th2 and Th17 types." (PMID 37476074, 2023). "Immunohistochemical expression profiles found that tumor-infiltrating CD4+ T cells statistically-significantly increased after treatment of these lung cancers with the combined regimen as compared to vehicle-treatments." (PMID 37689790, 2023). "In lung cancer, tumor-infiltrating CD4+ T cells play a crucial role in the immune response by allowing CD8+ T cells to enter tumor sites and infect mucous membranes to kill tumors; moreover, they are necessary to inhibit tumor angiogenesis." (PMID 37077811, 2023). "For example, we observed a CD6-ALCAM signaling pathway existing between DC (source) and TRM CD4+ T cells (target) in the lung cancer tumor microenvironment (TME)." (PMID 36810839, 2023). "Our findings are consistent with a previous report that CD4+ T cells were increased in the peripheral blood of older lung cancer patients compared to their younger counterparts." (PMID 37434467, 2023). "As of 12 August 2023, PubMed listed five articles under the search term of “ITGAL AND Lung cancer”, which studied ITGAL’s biomarker values in NSCLC and its association with CD4 memory cells in the TME of LUAD." (PMID 37835514, 2023). "Immunohistochemical tests among lung cancer patients showed that a large amount of immunosuppressive CD4+ T cells, including Th2 cells and Tregs, accumulated in the epithelium and stroma, whereas only a small number of Th1, Tfh, and Th17 cells were observed." (PMID 37857728, 2023). "In the current study, the results of analysis of lung cancer samples from the GEO single-cell dataset, RT-qPCR, and immunohistochemical analysis showed that T CD4+/CD8+ cell expression was correlated to TAGAP." (PMID 37744350, 2023). "CD4+ Th1 cells, activated by CD8+ T cells, and γδ-T cells predominantly contribute to type I immune responses and are associated with good prognosis in lung cancer patients." (PMID 37737709, 2023). "In our study, CD4+ Treg cells were found to be significantly elevated in all the lung cancer patients, with the highest Treg cell counts detected in the early recurrence patients before and after surgery." (PMID 37238744, 2023). "Our finding is consistent with a recent report showing that deletion of Areg in CD4+ T cells or Treg cells inhibits lung cancer." (PMID 37611111, 2023). "When lung cancer progresses, the number of tumor-related CD4+T cell clones decreased significantly, and the proportion of PD-1+T cells dropped." (PMID 37671151, 2023). "Our results also demonstrated a relatively lower density of CD4+ T cells in primary lung cancers (Case 2, 3, 5, and 7)." (PMID 37384291, 2023).
lung cancer (continued). "Mediastinal lymph nodes of patients with IPF had significantly higher PD-1 expression and CD4/CD8 ratio compared to patients with lung cancer, indicating distinct immune-mediated pathways regulating fibrogenesis and carcinogenesis." (PMID 37964265, 2023). "The study in lung cancer found that tanshinone IIA treatment significantly increased CD4+ and CD4+/CD8+ levels in vivo, as well as NK cell activity, further improving immune function and strengthen anti-tumor effect." (PMID 37964867, 2023). "EMT was found to be associated with significantly lower infiltration of CD4+ T cells and CD8+ T cells in lung cancer, as we have found in patients with BPC." (PMID 37392167, 2023). "Meanwhile, we found that CXCR3 and LFA-1 decreased in CD4+ T cells of patients with lung cancer (N = 6) compared to healthy volunteers (N = 14)." (PMID 36688994, 2023). "The median proportion of PD-1 + CD4 + or PD-1 + CD8 + cells in patients with lung cancer was found to be 66% and 77%, respectively." (PMID 37535195, 2023). "In lung cancer, activin activates pro-metastatic pathways to enhance tumor cell survival and migration while augmenting CD4+ to CD8+ communications to promote cytotoxicity." (PMID 37296966, 2023). "TSLP drove a significant CD4+ T cell response to block lung cancer progression from atypical alveolar hyperplasia to adenocarcinoma." (PMID 35565302, 2022). "In our study, the survival of advanced lung cancer treated with immunotherapy was significantly reduced in those patients with high baseline levels of CCR9+ or CCR10+ CD4+ T cells, or CXCR4+ CD8+ T cells." (PMID 35740564, 2022). "Studies have demonstrated the level of inflammatory cytokines is significantly higher and the level of CD4/CD8 is significantly lower in lung cancer and GGN patients as compared with that in patients with benign nodules." (PMID 36275807, 2022). "If the microenvironment of Carfilzomib‐treated lung cancers releases less chemoattractant, fewer CD4+ T cells are recruited into the tumor locus." (PMID 34898004, 2022). "We noticed more correlations among the subpopulations of T lymphocytes with CD8+ cells than with CD4+ cells in LNs with metastases of lung cancer patients." (PMID 35585972, 2022). "The CD4+CD25highFoxP3+ regulatory T cells, associated with tumor progression, were shown to express CXCR4 and be recruited into lung cancer." (PMID 35729596, 2022). "The peripheral blood of patients with lung cancer was collected and CD4+ T cells were obtained using immunomagnetic beads." (PMID 36434505, 2022). "Other studies have shown that a higher CD4/CD8 ratio of pleural effusion predicts better survival for lung cancer patients receiving immune checkpoint inhibitors." (PMID 35965524, 2022). "It was observed that patients with lung cancer had a higher percentage of CD4+IL-22+IL-17− cells, when compared to healthy controls (controls vs. lung cancer patients: 1.93 ± 0.25% vs. 6.06 ± 0.65%, P < 0.0001)." (PMID 35669104, 2022). "FACS analysis revealed that the percentage of Tregs (CD4+CD25+CD127low) among all CD4+ T cells ranged from 3.4% to 15.6% (mean, 8.29%) in 29 lung cancer patients and 5.2% to 12.5% (mean, 7.34%) in 34 healthy controls." (PMID 35197968, 2022). "Clinically, the presence of CD4+ T cells in the peripheral blood of lung cancer patients before immune checkpoint blockade therapy is associated with increased tumor-infiltrating CD8+ T cells and better response to PD-1 therapy." (PMID 35565302, 2022). "Intriguingly, we observed that TMPRSS2 expression correlated with infiltrating levels of CD8+ T cells, B cells, CD4+ T cells, neutrophils, macrophages, and dendritic cells in lung cancer." (PMID 35017320, 2022). "For example, autologous lung cancer cells induce TRAIL on tumor-infiltrating CD4+ CTLs contributing to tumor specific CD4+ CTLs mediated cell death." (PMID 36496977, 2022).
lung cancer (continued). "Transwell assays showed that the invasion and migration of lung cancer cells cultured with CD4+ T cell conditioned medium pretreated with propofol decreased notably." (PMID 36434505, 2022). "TSLP-activated CD4+ T helper 2 cells block early carcinogenesis by inducing terminal differentiation in spontaneous breast and lung cancer models." (PMID 36467403, 2022). "So we cultured human lung cancer cell line NCI-H1975 or normal lung epithelial cell line Beas-2B with CD4+ T cells (blank group) or CD4+ T cells pretreated with 30 μg/mL propofol (P group), respectively." (PMID 36434505, 2022). "By the way, the percentage of CD8+ PD-1+T cells was higher than that of CD4+PD-1+T cells in lung cancer patients (***P = 0.0001)." (PMID 36341395, 2022). "Lung cancer patients displayed a high concentration of CD4+, CD8+, and activated CD38+CD8+MAIT cells, and a decrease of PD1+ double negative (DN) MAIT cells in peripheral blood." (PMID 35371315, 2022). "The frequency of PD-1on CD4+T cells of lung cancer patients was lower than that of the control group (**P = 0.006)." (PMID 36341395, 2022). "CCK-8 assay showed that the viability of lung cancer cells cultured with CD4+ T cell conditioned medium pretreated with propofol decreased significantly (p < 0.05)." (PMID 36434505, 2022). "Then, we collected the peripheral blood of patients with lung cancer in vitro and obtained CD4+ T cells by immunomagnetic beads method." (PMID 36434505, 2022). "In cancer patients, a high density of tumor-infiltrating CD4 Th1 cells has been identified as a good prognostic marker in several human cancers, including lung cancer." (PMID 35546670, 2022). "This cancer suppression is dependent on CD4+ T cells, which highlights the role of adaptive immune response in protection against lung cancer progression." (PMID 35565302, 2022). "The same group also observed that Acidovorax temperans’ exposure in murine lung cancer models increases pro-inflammatory cells (mostly neutrophils), CD4+ T cells and CD4– CD8– T cells (including RORγt+ IL17+ T cells)." (PMID 36555915, 2022). "These antitumor effects were also observed in CD4+ T cells and macrophages: the polarization of M1 macrophages activated CD4+ T cells, facilitating cancer cell elimination in lung carcinoma." (PMID 34082692, 2022). "We selected differentially expressed genes for surface proteins of TI-Tregs and compared these with other CD4+ T cells using bulk RNA-sequencing data from murine lung cancer models." (PMID 33598101, 2021). "In this study, we explored the effects of the pleiotropic cytokine activin-A, on shaping anti-tumor CD4+ T cell-mediated responses in the context of lung cancer." (PMID 34548096, 2021). "Effector CD4+ T cells can differentiate into helper T cell (Th) subtypes which have been identified in MPE from people with lung cancer and mesothelioma." (PMID 33987104, 2021). "A further example is that, in lung cancer, tumor-infiltrating CD4+ T cells play an indispensable role in the immune response." (PMID 34858987, 2021). "In summary, our studies reveal that the cytokine activin-A enhances anti-tumor immunity orchestrated by CD4+ T cells, in the context of lung cancer." (PMID 34548096, 2021). "The ratio of CD3+ to CD4+ is used as a clinical assessment of the immune function of patients with lung cancer." (PMID 33936245, 2021). "Atanackovic and colleagues showed a strong peptide-specific Th1 type CD4 T cell response using a MAGE-A3 protein vaccine in patients with lung cancer." (PMID 34064410, 2021). "Compared with palliative platinum-based chemotherapy or gefitinib alone, add-on with Brucea javanica oil emulsion showed beneficial effects on KPS score and immune function including CD3, CD4, and CD4/CD8 level in lung cancer patients (3 RCTs)." (PMID 34025425, 2021). "In a translational approach, we validated activin-A’s anti-tumorigenic properties using primary human tumor-infiltrating CD4+ T cells from lung cancer patients." (PMID 34548096, 2021).
lung cancer (continued). "Of translational importance, treatment of activin-A on tumor-infiltrating CD4+ T cells from lung cancer patients augmented their immunostimulatory capacity towards autologous CD4+ and CD8+ T cells." (PMID 34548096, 2021). "The density of CD4-positive (CD4+) T-cells, CD8-positive T-cells, and CD4+ Foxp3-positive T-cells were statistically higher in both tumor and stromal areas in primary lung cancer specimens when compared with brain metastases samples (p < 0.0001)." (PMID 34647108, 2021). "To verify the 25 expression-based marker genes from the mouse lung cancer model in the human tumor, we utilized single-cell transcriptome data for CD4+ T cells from patients with NSCLC." (PMID 33598101, 2021). "Nevertheless, there is a significant gap in our knowledge regarding the role of activin-A in the modulation of anti-tumor CD4+ T cell-mediated immune responses in the context of lung cancer." (PMID 34548096, 2021). "Increasing evidence indicates that the massive infiltration of intracellular cytotoxic T lymphocytes (CD8+) and memory T cells (CD4+) in lung cancer is closely correlated to the good prognosis of patients with lung cancer." (PMID 33764442, 2021). "Overall, our study has laid the foundation for addressing key questions in the field of lung cancer immunology and foreseeing the exploitation of activin-A-conditioned CD4+ T cells in future therapeutic modalities, in the context of adoptive T cell therapy." (PMID 34548096, 2021). "Here, we first report that high hepcidin expression in lung cancer is correlated with the increased infiltration of B cells, CD4+ T cells, CD8+ T cells, neutrophils, macrophages, and dendritic cells." (PMID 33868231, 2021). "We further verified the anti-tumorigenic effect of activin-A signaling on CD4+ T cells, in a physiologically relevant chemically-induced model of lung cancer." (PMID 34548096, 2021). "In this study, low levels of T lymphocytes (p < 0.001), NK cells (p < 0.001), CD8+ T cells (p = 0.008), naïve CD4+/CD4+ (p < 0.001), and naïve CD4+ T cells (p < 0.001) was observed in lung cancer patients compared to controls." (PMID 34488711, 2021). "The results showed that CD3+, CD4+, CD4+/CD8+ in normally fed rats were elevated compared with those in lung carcinoma model rats, while CD8+ was declined (P < 0.05)." (PMID 34399782, 2021). "The level of CD4+CD25+CD127-Tregs in peripheral blood of patients with lung cancer is positively correlated with plasma IL-10 level." (PMID 32218692, 2020). "The TLR7 antagonist Loxoribin inhibited tumor growth in xenograft models of colon cancer and lung cancer by promoting CD4+ T cell proliferation, reversing CD4+CD25+ Treg-mediated suppression via DCs." (PMID 32746880, 2020). "We found that ACK1 gene copy numbers were inversely associated with the infiltration levels of B cell, CD8+ T cell, CD4+ T cell, macrophage, neutrophil, and dendritic cells in lung cancer." (PMID 32793482, 2020). "More importantly, detection of T lymphocyte subsets undertaken by flow cytometric analysis found that CD4+ T lymphocytes remarkably accumulated during radioactive pneumonia period in patients with lung cancer." (PMID 32207253, 2020). "Previous studies found that the role of CD4+ T cells in antitumor activity of lung cancer is dualistic (Zheng, Hu & Yao, 2017)." (PMID 32206449, 2020). "Most importantly, we found lung cancer patients to have higher percentages of platelet-T cell aggregates (PTCAs) than healthy volunteers among both CD4+ T lymphocyte and CD8+ T lymphocyte populations." (PMID 32776968, 2020). "Luo demonstrated that patients with lung cancer have greater CD4+ cells than those in the healthy control group." (PMID 32459060, 2020). "One explanation for this finding is that CD4+ T cells were activated and differentiated into memory CD4+/CD4+ T cells in lung cancer patients." (PMID 32459060, 2020).
lung cancer (continued). "Though C3 was reported to associated with CD4+ and CD8+ T lymphocytes in lung cancer, however, a majority of studies suggested that C3 play an oncogenic role in multiple cancers." (PMID 33732636, 2020). "A similar pattern of lymphocyte expansion driven by the increased CD4+ T cell clonality is also evident in lung cancer patients with COPD." (PMID 32117295, 2020). "Our results showed that lung cancer patients had higher numbers of memory CD4+/CD4+ T cells than healthy controls." (PMID 32459060, 2020). "Dysregulated immune function is a hallmark of lung cancer and COPD, with both diseases sharing similar inflammatory cell profiles characterized by macrophages, neutrophils, and CD4+ and CD8+ lymphocytes." (PMID 31911640, 2020). "We recently observed that the addition of anti-PD-1 or anti-PD-L1 blocking was able to restore the function of hTERT-specific CD4+ Th1 response in lung cancer patients treated by Nivolumab." (PMID 32957741, 2020). "Naïve CD4+ cells incubated with MT KRAS TDEs isolated from human lung cancer cells were used as a control." (PMID 31635338, 2019). "Another study reported increased CD8+CD28− T cells and CD4+CD25hi T cells in advanced lung cancer patients." (PMID 31623615, 2019). "For instance, a study by Adusumilli et al56 showed that the therapeutic efficacy of MSLN‐CAR‐T therapy for lung cancer was dependent on early CD4+T cell activation and CD4+T cell‐mediated cytotoxicity, but not CD8+T cells." (PMID 31339230, 2019). "In conclusion, we found important differences in PD-1 and CTLA-4 expression on CD8+ and CD4+ cells depending on the status of their activation in the lung cancer microenvironment." (PMID 31010080, 2019). "We compared the CD3/CD19, CD4/CD8, and Treg/CD4 ratios in lymph nodes from age-matched patients (60–79 years old) from two groups (sarcoidosis and lung cancer)." (PMID 30452447, 2018). "In our murine lung cancer model, we found a significantly reduced secretion of soluble TNFα by M1 macrophages and impaired secretion of soluble TNFα by CD4+ and CD8+ T cells." (PMID 30647851, 2018). "Recent studies have demonstrated a relationship between low CD4 count and lung illnesses including lung cancer and Chronic Obstructive Pulmonary Disease (COPD)." (PMID 30148202, 2018). "The oncomiR hsa-mir-21 is frequently upregulated in lung cancer while it is downregulated in CD4+ T cells in tuberculosispatients." (PMID 30237679, 2018). "Next we addressed the number of CD4+CD25+Foxp3+ T regulatory cells induced by DC-based HHP lung cancer vaccine after 7 days." (PMID 28187172, 2017). "Among the six subgroups, the elderly lung cancer patients exhibited the highest levels of both CD4+CD25+FOXP3+ Treg (11.81 ± 2.40%) and FOXP3 mRNA (3.14 ± 1.30)." (PMID 28253320, 2017). "In 36 NSCLC patients we detected IFN-γ-producing CD8+ and CD4+ T cells responsive to the all tested antigens which support our findings that our DC-based HHP lung cancer vaccine is fully competent to induce anti-tumor T cell responses in NSCLC patients." (PMID 28187172, 2017). "This study was designed to explore the relationship between increase in CD4+CD25+FOXP3+ Treg and the higher risk of lung cancer in the elderly." (PMID 28253320, 2017). "Tumor antigen specific CD8+ and CD4+ T cell responses were detected in NSCLC patient’s against a selected tumor antigens expressed by lung cancer cell lines used for the vaccine generation." (PMID 28187172, 2017). "The effect of IL-17 production on the CD4+ memory T cells in human lung cancer requires further investigation." (PMID 28101811, 2017). "CD4+CD25+Foxp3+ Tregs with immunosuppressive capacity are enriched in lung cancer tumor-infiltrating lymphocytes." (PMID 28472762, 2017). "The accumulation of CD4+CD25+FOXP3+ Treg with age correlates well with the increasing incidence of lung cancer in the elderly." (PMID 28253320, 2017). "Meanwhile, lung cancer patients had a higher concentration of CD4+CD25+Foxp3+ cells (Treg) in PBMCs." (PMID 28178645, 2017).